IL1B (interleukin 1 beta)
Diseases named in the same sentence as IL1B in open-access papers (continued):
Sharing a sentence is not in itself a finding about the gene and the disease.
infection (continued). "This was particularly evident in individuals with past symptomatic infection (designated Group 5): C. burnetii antigen-stimulated whole blood from these individuals showed elevated bulk release of IL-1β as well as increased IL-6 production by monocytes as detected by flow cytometry." (PMID 37885896, 2023). "For example, evasion of immune surveillance by suppression of IL1B was proposed to be largely dictated by virulence of the M.tb strain; however, expression of differentially expressed (DE) genes during infection with a single M.tb strain can vary > 10-fold between individuals." (PMID 37333188, 2023). "To determine whether this model elicits a pro-inflammatory response, similar to what has been shown previously using shorter infection times, we analyzed mRNA expression levels of IL-1β, IL-6 and CXCL8 (IL-8) along with protein levels of IL-8 in our model." (PMID 37432929, 2023). "Infection stages are characterized by an accumulation of myeloid cells around the necrotic area and the production of large amounts of inflammatory cytokines, such as IL1β." (PMID 37428812, 2023). "One previous study has indicated that the distinct signature for severe infections includes a double peak of serum IL-6 levels, and high serum levels of IL-8 and IL-1β, which may aid in differential diagnosis between severe infection and CRS51,79." (PMID 36861439, 2023). "Furthermore, proinflammatory cytokine genes il1β and tnf-α were upregulated during infection, recapitulating key immune responses seen in human infection." (PMID 37155695, 2023). "When we examined macrophage gene expression after infection with ∆ppsD by qPCR, we found that expression of Il1b, Il6, Nos2, and Tnf was significantly increased compared to infection with WT Mtb, consistent with the idea that PDIM reduces inflammatory signaling." (PMID 36852737, 2023). "TNF-α and IL-1β sequentially activate the local endothelium, induce vasodilation, increase vascular permeability, and enable the recruitment of serum proteins and leukocytes to the site of infection." (PMID 36765373, 2023). "IL-1β, due to its pro-inflammatory and pleiotropic biological activity, plays a central role in orchestrating the innate immune responses following a wide range of conditions, including infections." (PMID 37175768, 2023). "Moreover, biological processes, such as positive regulation of interleukin-1 beta production, inflammatory response and positive regulation of NF-κB transcription factor activity, were significantly upregulated post infection." (PMID 38093309, 2023). "Furthermore, high expression of IL-1β was also found in different carp lines at days 3 and 5 post-infection challenged with CyHV-3." (PMID 37465154, 2023). "Furthermore, qRT-PCR analysis of proinflammatory genes indicated significantly increased levels of Cxcl10, Il-1b, and Tnf, especially at 72 h post-infection." (PMID 37426673, 2023). "In addition, the release of TNF-α and IL-1β induced by BCG (MOI = 10) infection was reversed by siRNA-DUSP1 transfection, indicating that DUSP1 knockdown inhibited the BCG-induced inflammatory response in THP-1 cells." (PMID 36788275, 2023). "Infection with ASFV ∆H240R in porcine alveolar macrophages (PAMs) produces higher IL-1β." (PMID 37631977, 2023). "Meanwhile, the IL-1β gene was upregulated significantly only at days 7 and 14 post-infection." (PMID 37337042, 2023). "In addition, after infection or injury, the cytokine IL-1β is produced in bone marrow and promotes myeloid differentiation through activation of the NF-κB pathway that results in the expansion of hematopoietic stem and progenitor cells (HSPCs)." (PMID 37577033, 2023). "In addition to their direct antimicrobial functions, neutrophils can release proinflammatory cytokines, including TNF-α and IL-1β, which promote local inflammation and recruit other immune cells to the site of infection." (PMID 37895050, 2023).
infection (continued). "The increase in il-1β expression in these mucosal organs may result in increased mucus secretion, which could be advantageous during a T. maritimum’s infection." (PMID 37731496, 2023). "Therefore, we evaluated the effect of mucosal co-delivery of porcine IL-1β on local and systemic B and T cell responses in inbred Babraham pigs and compared it to immunity induced by natural pH1N1 infection." (PMID 37153548, 2023). "As for the results of IL-1β, they guided us to our previous studies, which revealed that IL-1β was upregulated by our stimulant at the early stage of infection, but it was downregulated to maintain the normal inflammatory level after the invaded bacteria were cleared." (PMID 36232768, 2022). "Indeed, during early lung infection with TIGR4 despite reduced BALF TNF levels, the levels of IL‐1β were increased compared to infection with TIGR4Δply." (PMID 35835695, 2022). "After infected with Yersinia pseudotuberculosis, the highest infection-induced immunomodulatory genes were those of the major proinflammatory cytokines: interleukin-1 alpha (il1a), interleukin-1 beta (il1b), interleukin-6 (il6), interleukin-17F (il17f) and interferon gamma (ifng)." (PMID 36059501, 2022). "Furthermore, recent studies have shown that infection by picornaviruses such as rhinovirus, coxsackievirus B3 (CVB3), poliovirus, and EV-A71 results in IL-1β secretion and is also associated with the activation of the NLRP3 inflammasome." (PMID 36503883, 2022). "In addition, duLGP2 upregulated the expression of duRIG-I mediated several key pro-inflammatory cytokines during DTMUV infection, including IL-1β, -2, -6, and -8." (PMID 35784309, 2022). "During STEC O113 ΔsubAB infection, Tm also inhibited IL-1β production." (PMID 35345462, 2022). "The interleukin-1 (IL-1) family members IL-1α and IL-1β, which are also proinflammatory cytokines, are produced by macrophages, DCs, and neutrophils during Mtb infection and are important in the early defense against infection." (PMID 36365041, 2022). "Our data showed that ECHO 11 infection or LPS/Nigericin treatment induced pro-IL-1β maturation, and CASP-1/GSDMD cleavages in THP-1 cells, and these activations were remarkably attenuated by knocking down either one of the NLRP3 inflammasome components and pyroptosis." (PMID 36026486, 2022). "Similarly, IL-1β and iNOS upregulations were also recorded following infection with other avian respiratory pathogens, such as IBV and LPAIV." (PMID 35632538, 2022). "Similarly, while holding day constant, infection status maintained a significant influence on Ifnγ, Il1β, Il10, and Cox2 abundance (p ≤ 0.0273), with tendencies for Tnf and Cox1 (p = 0.0569 and p = 0.0645, respectively)." (PMID 35312688, 2022). "The levels of inflammatory factors in the colon tissues of CRKP colonization-challenged mice were significantly higher than those in normal mice, with significantly enhanced TNF-α, IL-1β, and IL-6 expression, and translocated infection further enhanced the expression of IL-6." (PMID 36445086, 2022). "In this study, we investigated expression of pro-inflammatory cytokine genes in epithelial cells infected with HAdV26 and found that HAdV26 infection of human epithelial cells triggers the expression of pro-inflammatory cytokines, namely IL-6, IL-8, IL-1β, and TNF-α." (PMID 35458402, 2022). "The invasion of and damage to the bronchial mucosa by M. haemolytica may promote the production of inflammation (e.g., IL-1β release) and the formation of infection foci." (PMID 35777914, 2022). "Additionally, ASFV-Δ9L/Δ7R infection exhibited dramatic induction of genes important during the acute-phase response, such as IL-1A, IL-1B, IL-10, and IL-18, tumor necrosis factor alpha (TNF-α), and several members of the complement pathway (C1R)." (PMID 35867564, 2022). "Infection of Il-1β−/− or Il-1α−/− BMDMs with Rickettsia spp." (PMID 35130729, 2022).
infection (continued). "Therefore, this study aimed to investigate the bacterial load, the ROD21 excision, the IL-1β, IL-8, and INF-γ blood serum concentration kinetics, and the association with the H/L ratio in chicken at 1, 3, 7, and 21 days post-SE infection." (PMID 35056020, 2022). "The observations showed that ECHO 11 infection induced IL-1β secretion and LDH release gave us a hint that ECHO 11 infection may induce inflammasome activation and pyroptosis." (PMID 36026486, 2022). "In this study, SFTSV infection induced processing of pro-caspase-1 and subsequent maturation and secretion of IL-1β/IL-18 were significantly suppressed in human PBMCs when NLRP3 gene was knocked down by specific shRNA or inhibited by a specific inhibitor, glibenclamide." (PMID 35173184, 2022). "The phage cocktail revealed anti-inflammatory effects when administered either 1 day after infection or 2 days after S. Typhimurium detection in feces, as measured by inhibition of the increase in levels of inflammatory response markers (IL-1β, IL-6, IFN-γ, IL-8, and IL-12)." (PMID 36211337, 2022). "To address whether Casp-1 is involved in SVA-induced IL-1β production, we assessed IL-1β secretion and IL-1β maturation form expression in BMDM cells after SVA infection." (PMID 35254168, 2022). "In addition, ASFV-ΔH240R infection induced higher expression of proinflammatory cytokines, including IL-1β, IL-6, TNF-α, and C-X-C motif chemokine ligand 8, in PAMs than did ASFV-WT infection." (PMID 36326277, 2022). "An excessive release of inflammatory factors, including IL-6, IL-12, IL-1β, and TNF-α, from immune disorders caused severe apoptotic damage to immune organs, which was consistent with MG-Rlow infection-induced damage to the spleen, thymus, and bursa of fasciola." (PMID 36139393, 2022). "IFNγ, IP-10 and IL-2 responses were strongly elevated in individuals with prior C. burnetii antigen exposure, whether through infection or vaccination, while IL-1β, IL-6 and TNFα responses were slightly increased in naturally exposed individuals only." (PMID 35812430, 2022). "During the acute stage of infection, both IL-6 and IL-1β are known to be expressed." (PMID 35531475, 2022). "The data demonstrated that Casp-1 is involved in the activation of IL-1β during SVA infection." (PMID 35254168, 2022). "Thus, the knockdown of inflammatory components of NLRP3 decayed IL-1β activation during SVA infection." (PMID 35254168, 2022). "This might be the result of the increased il-1β production during the early infection, as il-1β has been shown to be a potent stimulus for neutrophil recruitment." (PMID 35693809, 2022). "released significantly lower levels of IL-1β and IL-1α than infection of WT BMDMs." (PMID 35130729, 2022). "However, infection of neutrophils with P. aeruginosa PAO1 deficient for ExoS triggered significantly increased lysis, membrane permabilization and IL-1β release." (PMID 35849616, 2022). "The level of IL-1β secretion in response to infection by H37Rv was 122.54 pg/mL." (PMID 36000264, 2022). "As infection progressed to 7, 14, and 21 dpi, we observed marked reductions in multiple cytokines (including interleukin-1 β [IL-1β] and IL-4) and leukocytes (including CD45+ cells and alveolar macrophages) in mar1Δ mutant strain-inoculated lungs compared to WT strain-inoculated lungs." (PMID 35587201, 2022). "IL-1β plays an important role in the control of infection by various pathogens." (PMID 36326277, 2022). "Additionally, ASFV HLJ/18 strain infection-induced IL-1β production is depended on TLRs/NF-κB signaling pathway and NLRP3 inflammasome." (PMID 35350623, 2022). "In the spleen after challenge with S. iniae, the relative gene expression of IL-1β in the BI and MS groups showed a significantly higher peak (p < 0.05) at 24 h post-infection (hpi) (8.2-fold in BI- and 5.1-fold in MS-vaccinated fish) than the unvaccinated treatment." (PMID 36138746, 2022).
infection (continued). "In support of this hypothesis, large increases in serum IL-1β values have been observed in response to an acute infection or to BPA." (PMID 35628520, 2022). "However, some findings regarding to IL-1β are contradictory: in vitro infection of murine primary osteoblasts with S. aureus resulted in increased transcription, but not in increased protein synthesis or secretion." (PMID 36483565, 2022). "Previous studies on human enterovirus 71 (EV71), belonging to EV-A, have shown that its infection induces the production and secretion of IL-1β in THP1 cells, macrophages, and peripheral blood mononuclear cells (PBMCs), and mouse bone marrow-derived macrophages (BMDMs)." (PMID 36026486, 2022). "Taken together, these suggest the signal for intracellular pre-IL-1β processing may require the interaction of different cell types, the 3D skin structure, or an infection with live D. nodosus." (PMID 36496756, 2022). "The higher the IL-1β and IL-6 levels, the more serious the infection." (PMID 35531475, 2022). "Similarly, E. coli 1587 infection elevated the transcription levels of IL-1β, IL-6, TNF-α, and IL-10 in the colonic tissues, while TGF-β was decreased." (PMID 35643532, 2022). "However, after 8 dpi, the cytokine concentrations of IFN-γ, TNF-α, and IL-1β in BCGΔRS01790 infection group were lower or similar compared with the other two infection groups at one or more time points." (PMID 35281073, 2022). "Inflammasome activation with cleavage of caspase-1 and secretion of IL-1β is not affected in the absence of caspase-7, as well as induction of cell death and in vivo susceptibility to infection." (PMID 36532444, 2022). "Similarly, JWH133 treatment resulted in reduced IL-1β release from mouse primary AMs in response to PA infection as observed by lower IL-1β levels in the supernatant of AMs treated with JWH133 as compared to that of vehicle-treated AMs." (PMID 36463179, 2022). "Besides, NO is one biomarker because during the pathogen’s infection process, the immune cells improved pro- IL-1β, TNF-α and INF-γ through promoting NO production." (PMID 36296333, 2022). "First, we determined the effect of SVA infection on IL-1β secretion and production in pigs." (PMID 35254168, 2022). "On the other hand, ASFV-ΔH240R infection induced high levels of IL-1β production in PAMs." (PMID 36326277, 2022). "In addition, using RT-qPCR the low-level expression of IL1B was detected in WT cells during infection, whereas it remained undetectable in YAP-/- infected and uninfected cells." (PMID 36384856, 2022). "When infection is present during pregnancy, inflammatory products—such as those associated with congenital infections and III—trigger microglial activation, resulting in neuroinflammation marked by the presence of IL-1β, TNF-α, and IL-6." (PMID 35844234, 2022). "Moreover, during infection, there is an increase in proinflammatory cytokines (interleukin (IL)-1α, IL-1β, IL-6, IL-8, IL-18, tumor necrosis factor (TNF)-α, IFN-γ, leading to a disbalance in immune surveillance mechanisms and changes in the tissue environment." (PMID 36294658, 2022). "Released IL-1β recruits immune cells to the site of infection/injury." (PMID 35663964, 2022). "Since P. acnes can induce the secretion of IL-1β, it may affect the ability of cells to fight infection and disease." (PMID 35871079, 2022). "In order to test whether SEZ would trigger the secretion of IL-1β and IL-18 in vivo, cytokine levels in PLF were measured by enzyme-linked immunosorbent assay (ELISA) after 24h-infection." (PMID 36311722, 2022). "Interestingly, duRIG-I-CARD- or full-length duRIG-I- (DTMUV infection) mediated pro-inflammatory cytokines (IL-1β, IL-2, IL-6, IL-8) expression level was significantly promoted by overexpression of duLGP2." (PMID 35784309, 2022). "The failure of eugenol to significantly reduce IL-1β may be related to the potential infection sites of the virus and the action sites of eugenol." (PMID 36052062, 2022).
infection (continued). "IL-1β was also measured in the culture medium; however, it was undetectable until 24 h post-infection (9116 ± 3930 pg/g of tissue in the CHD and 6150 ± 4830 pg/g of tissue in the AMN, p < 0.05 vs. control values, which were considered as zero since they were below the detection limits of the assay)." (PMID 35328414, 2022). "We have preliminary data at this stage to indicate that platelets may also secrete IL-1β with pro-caspase-1 processed upon infection with SFTSV." (PMID 35173184, 2022). "In addition to characterizing the ability of the Salmonella to induce cell death, we assessed the ability of our Salmonella isolates from the spleen and gallbladder to induce IL-1β secretion upon infection of BMMs." (PMID 34864057, 2022). "Our data show that recognition of T3SS-expressing P. aeruginosa strains by the caspase-1 dependent canonical inflammasome leads to pro-inflammatory responses, manifested by increases in caspase-1-activation, IL-1β, and IL-18 cytokine production, and leukocyte migration to the site of infection." (PMID 35277504, 2022). "In this effort, BMDMs derived from WT, Casp-1−/−, Casp-11−/−, and Casp-1/11−/− mice were infected with R. typhi, R. rickettsii, and R. montanensis, and the levels of IL-1β and IL-1α and cell death, as well as bacterial burdens, were evaluated over the course of infection." (PMID 35130729, 2022). "In addition, the levels of filaggrin, VEGF, MIP-1β, RANTES/CCL5, HIF-1α and IL-1β were identified as infection biomarker molecules with AUC values > 0.72, having the next values of specificity (> 79%) and sensitivity (> 55%)." (PMID 36482106, 2022). "Plasma IL-1β and C3 were quantified 0, 2, 4, 8, 12, 16, 24, 48, and 96 h post-infection." (PMID 36026499, 2022). "Furthermore, NAIP-/- and NLRC4-/- THP-1s treated with MCC950 secreted negligible levels of IL-1α, IL-1β, and IL-18, similar to those observed during ΔsipB Stm infection." (PMID 35073381, 2022). "Similarly, ESBL-EAEC infection elevated transcription levels of IL-1β, IL-6 and TNF-α in colonic tissues, but recovered after GA administration with an obvious decline of IL-10 and TGF-β." (PMID 35399688, 2022). "Our results indicate that infection with WT GBS significantly enhanced the production of IL-1β, MIP-1α, and TNF-α in the uterus, decidua, placenta, amnion, and fetus compared to the uninfected controls (*, P < 0.05 by one-way ANOVA; #, P < 0.05 by Student’s t test)." (PMID 36409087, 2022). "Interestingly, CRP, AAT, and SLPI specifically inhibit the ATP (trauma)-induced release of IL-1β, while sparing the ATP-independent inflammasome activation against pathogens, which is vital in the context of severe injuries and infections." (PMID 36105198, 2022). "Most importantly, the biological effects of SVA infection on the induction of IL-1β responses were evaluated in mice and natural hosts, and the results showed that the IL-1β mRNA level and protein production in the heart, kidney, liver, and spleen became stronger in 3D-expressing pigs." (PMID 35254168, 2022). "However, among patients who received a monoclonal antibody against IL-1β, adverse events, such as infection, are frequently reported." (PMID 35351143, 2022). "IL1B is a well-known cytokine secreted by activated phagocytes (e.g., macrophages) to trigger an inflammatory response in the surrounding tissue in response to injury or infection." (PMID 35418993, 2022). "LL-37 may also prepare astrocytes for infection by gearing them into a pro-inflammatory state with upregulated IL-1β and IL-6, but this inflammatory state must be reduced upon infection to prevent chronic inflammation and disease." (PMID 35634307, 2022). "Of note, three of the four genes that were significantly regulated in all investigated conditions showed lessened induction upon concomitant infection and Smh1 expression (IL-1β, GLIS3, and MIR3142HG), while down-regulation of the fourth factor (RGS4) is accentuated by Smh1 expression." (PMID 36411449, 2022).